TLR4 (toll like receptor 4)
Diseases named in the same sentence as TLR4 in open-access papers (continued):
Sharing a sentence is not in itself a finding about the gene and the disease.
acute liver failure (19 papers, 2012 to 2025). Rapid deterioration of liver function causing encephalopathy and coagulopathy. "As illustrated above, UDCA-LPE demonstrated potent anti-inflammatory properties in vivo in a mouse model for acute liver failure as well as in the macrophage cell line RAW264.7 by directly downregulating the TLR4 pathway." (PMID 29795632, 2018). "This study therefore raises the possibility of therapeutic intervention to modify intestinal microbiota through gut cleansing antibiotics or pharmacological inhibition of TLR4 signalling in the treatment of patients with acute liver failure." (PMID 25244648, 2015). "We found that the mRNA expressions of HMGB1, TLR4, and NF-κB were remarkably increased in acute liver failure model group." (PMID 23554835, 2013). "Some results show that TLR4 expression was decreased in acute liver failure; another study showed that TLR4 expression was significantly increased with the liver injury." (PMID 23028846, 2012). "In acute liver failure, the expression of TLR4 of hepatic cell and its effects is still some controversy." (PMID 23028846, 2012). "Collectively, diacerein ameliorated cerebral edema and maintained BBB integrity via modulation of TLR4/AQP4/MMP-9 axis thus may decrease the progression of HE induced in acute liver failure." (PMID 39556255, 2024). "CGA-JK3 ameliorated E. coli lipopolysaccharide (LPS, MD-2/TLR4 agonist)-induced endotoxic shock, cecal ligation and puncture (CLP)-challenged septic shock or LPS plus D-galactosamine (GalN)-induced acute liver failure (ALF) in C57BL/6J mice." (PMID 28145460, 2017). "Hepatic TLR4 expression was reduced by recAP in ACLF but not acute liver failure." (PMID 31942020, 2020).
acute myeloid leukemia (19 papers, 2016 to 2025). Acute myeloid leukemia (AML) is a group of neoplasms arising from precursor cells committed to the myeloid cell-line differentiation. "The results of in-silico analysis suggested that the expression of TLR4 in tumor tissues was significantly higher in acute myeloid leukemia than in normal tissues." (PMID 36281200, 2022). "In order to understand the ability of redox-dependent ASK1-mediated activation of AP-1 in TGF-β and galectin-9 production, we used THP-1 human acute myeloid leukaemia cells which express Toll-like receptor 4 (TLR4)." (PMID 33295886, 2020). "The use of this TLR4 inhibitor has been evaluated in clinical trials for the treatment of refractory acute myeloid leukemia (AML) and myelodysplastic syndrome (MDS)." (PMID 34884547, 2021). "Additionally, acute myeloid leukemia (AML) cells uptake exogenous palmitate via CD36, activating ZDHHC6-mediated MYD88 palmitoylation to potentiate the TLR4-LYN-MYD88-NF-κB signaling axis." (PMID 40977744, 2025). "S100A9 induces acute myeloid leukemia (AML) cell differentiation through TLR4–MAPK/ERK–JNK signaling, whereas S100A8 prevents differentiation induced by S100A9 activity and maintains the AML immature phenotype." (PMID 29942307, 2018). "The pattern-recognizing receptor known as toll-like receptor 4 (TLR4) is expressed by acute myeloid leukemia (AML) cells, many bone marrow stromal cells, and nonleukemic cells involved in inflammation." (PMID 39221252, 2024). "In other hematological cancers, such as acute myeloid leukemia (AML), the mRNA expression levels of TLR2 and TLR4, but not of TLR9, were increased, contrary to what was observed in ALL, and expression of TLR7 and 9 was decreased in chronic myeloid leukemia (CML)." (PMID 34567117, 2021).
cystic fibrosis (19 papers, 2010 to 2025). Autosomal recessive disorder caused by pathogenic variants in the CFTR gene (cystic fibrosis transmembrane conductance regulator), which encodes a chloride and bicarbonate channel expressed in epithelial cells, and follow the diagnosis criteria. "Macrophages (MΦs) with mutations in cystic fibrosis transmembrane conductance regulator (CFTR) have blunted induction of PI3K/AKT signaling in response to TLR4 activation, leading to hyperinflammation, a hallmark of cystic fibrosis disease." (PMID 28883468, 2017). "Such a molecular mechanism has been recently described in cystic fibrosis patients who displayed altered regulation of Toll-like Receptor-4 splice variants." (PMID 20534143, 2010). "Several natural products isolated from medicinal plants deserve attention and pre-clinical studies in the field of therapeutic intervention for cystic fibrosis using inhibitors of the TLR4/NFκB pathway." (PMID 41226119, 2025). "In cystic fibrosis cells, the loss of functional CFTR impairs the normal endocytic and lysosomal trafficking of TLR4, which remains in early endosomes, failing to be degraded." (PMID 41226119, 2025). "In other studies, increased expression of TLR4 was detectable in intestinal tissues of mice that had developed cystic fibrosis and TLR4 also mediated the survival of bacteria in the tissues." (PMID 40044628, 2025). "In LPS-stimulated cystic fibrosis macrophages, TLR4 signaling is activated and the stress-induced expression of HO-1 is recruited to the cell surface with cav-1, suppressing TLR4-mediated signaling by CO generation." (PMID 31396090, 2019). "Dysregulation of TLR4 expression or localization at the epithelial interface results in impaired host response to LPS as observed in cystic fibrosis." (PMID 27765038, 2016). "The soluble TLR4 isoform expression after exposure to LPS is significantly less in monocytes from patients with cystic fibrosis." (PMID 25955250, 2015). "In addition, miR-199a-5p, another miRNA found to be downregulated in HIV+/TB+, was demonstrated to have a positive relationship with TLR-4 signaling and IL-6 expression in macrophages in a cystic fibrosis model." (PMID 35295678, 2021). "Likewise, Pseudomonas aeruginosa expresses a modified LPS which promotes evasion of TLR4 signaling, favors intracellular survival, and has been postulated to contribute to chronic persistence in Cystic Fibrosis patients." (PMID 25010102, 2014). "A putative negatively acting splice form of TLR4 has been examined in monocytes from a cohort of subjects with Cystic Fibrosis." (PMID 36531997, 2022). "Concerning other TLRs, Mizunoe and colleagues reported that IL-17A enhanced the production of IL-8 induced by peptidoglycan (TLR2 agonist) or lipopolysaccharide (TLR4 agonist) in bronchial epithelial cells from cystic fibrosis patients, but not in NHBE cells." (PMID 26418032, 2015). "For example, human TLR4, but not murine TLR4, can discriminate between the hexa- and penta-acylated forms of LPS produced by Pseudomonas aeruginosa from the airways of cystic fibrosis patients." (PMID 25071777, 2014). "The information on the effects of AGE, SAC and S1PC on cystic fibrosis is still lacking, although inhibition of TLR4/NFκB-dependent expression of pro-inflammatory genes might occur and should be considered." (PMID 41226119, 2025). "Interestingly, a reduced inflammatory response to stimulation with LPS from Gram-negative bacteria in cystic fibrosis airway epithelial cells has previously been attributed to a lower surface expression of surface TLR-4, a finding which is reflective of our experiments using CSE." (PMID 22412951, 2012). "In addition, regulation of immune activation, including TLR4 activation in alveolar macrophages and epithelial cells, appears to be dysregulated in CF patients, in part due to the lack of a functional cystic fibrosis transmembrane conductance regulator (CFTR) (26, –, 28)." (PMID 28947647, 2017).
cystitis (19 papers, 2009 to 2025). Inflammation of the urinary bladder. "Several lines of evidence point to the involvement of TLR4 in neuroinflammation and cystitis-associated chronic pain, as summarized below." (PMID 38249555, 2023). "In contrast to our model, the mothers became septic and all of the fetuses became infected, presumably due to the use of a pyelonephritic UPEC strain (compared to our cystitis strain) and the use of immunocompromised TLR4-deficient mothers." (PMID 22470490, 2012). "Reduced expression levels of CXCR1 and TLR4 in neutrophils are associated with pyelonephritis, recurrent cystitis, and asymptomatic bacteriuria in children and premenopausal women." (PMID 21151974, 2010). "Mice deficient in TLR4 signaling or lymphocytes lack these innate responses and are resistant, to varying degrees, to developing chronic cystitis." (PMID 20811584, 2010). "CYP-associated cystitis is likely a result of a complex crosstalk with a number of contributing factors that can include ROS production, oxidative stress, and TLR4 signaling, which in turn can increase the expression of inflammasome components, in particular the NLRP3 inflammasome." (PMID 38271096, 2024). "In addition, reduced expression levels of CXCR1, CXCR2 and TLR4 on neutrophils was associated with pyelonephritis, recurrent cystitis and asymptomatic bacteriuria, respectively." (PMID 19543401, 2009). "This evidence supports the involvement of TLR4/NF-κB signalling in the pathogenesis of CYP-induced IC, highlighting its potential as a key modulator in the inflammatory response associated with cystitis." (PMID 40133553, 2025). "Studies have demonstrated that either genetic deletion or pharmacological inhibition of TLR4 can effectively prevent bladder inflammation in mouse models of cyclophosphamide (CYP)-induced cystitis." (PMID 40133553, 2025). "The inflammatory responses in systemic and central derived by TLR4 activation were closely related to the cystitis‐induced pelvic/bladder nociception in IC/BPS model." (PMID 38415918, 2024). "Intrathecal injection of miR‐9‐enreched MSCs derived exosomes were effective in the treatment of cystitis‐induced pelvic/bladder nociception by inhibiting TLR4/NF‐κb/NLRP3 signal pathway in central nervous system of IC/BPS mice." (PMID 38415918, 2024). "Previously, we verified that glucose promotes UPEC-induced cystitis and invasion into uroepithelial epithelial cells by activating TLR-4-mediated UPEC infection and JAK/STAT1-dependent pathways." (PMID 34946023, 2021). "Uropathogenic E. coli activate IL-1β through a TLR4-dependent signaling pathway and as a result the acute cystitis phenotype is attenuated in Tlr4−/− and Il1b−/− mice." (PMID 30030504, 2018). "Although previous studies in mice indicate that TLR4, TLR5, and TLR11 regulate susceptibility to cystitis and pyelonephritis, the role of TLRs in human UTI pathogenesis is poorly understood." (PMID 19543401, 2009). "We have previously verified that TLR4‐deficient URO‐OVA mice developed significantly reduced bladder nociceptive responses, although similar bladder inflammation and voiding dysfunction, after cystitis induction." (PMID 38415918, 2024). "Collectively, these results suggest that intrathecal injection of hUMSCs overexpressing HO-1 can significantly promote functional outcomes in cystitis rats by reducing neuroinflammation, at least, partly through downregulating TLR4/p65/NLRP3 pathway in the SDH region of CYP-induced cystitis rats." (PMID 38020203, 2023). "Our results suggest that injecting hUMSCs overexpressing HO-1 intrathecally can significantly promote functional outcomes in cystitis rats by reducing neuroinflammation, at least, partly through downregulating TLR4/p65/NLRP3 signaling pathway in the SDH region." (PMID 38020203, 2023).
cystitis (continued). "We also show that parity-associated increased severity of UPEC cystitis was aided by TLR4- signaling in the bladder but not the kidney, since C3H/HeJ mice deficient for TLR4-signaling have less severe cystitis." (PMID 24835885, 2014). "However, unexpectedly we found that C3H/HeJ mice, which are incompetent for TLR4 signaling, had significantly lower levels of bladder infection compared to C3H/HeOuJ mice at 4 wpi." (PMID 20811584, 2010). "Since previous work had demonstrated that UPEC infection of both C3H/HeJ and C3H/HeOuJ mice resulted in similarly high bladder titers at 14 dpi, it had been hypothesized that chronic cystitis occurred independently of TLR4 signaling." (PMID 20811584, 2010). "Finally, we proved that EVs derived from miR‐9‐modified mesenchymal stem cells could alleviate neuroinflammation and cystitis‐induced bladder pain by inhibiting TLR4/NLRP3 pathway in interstitial cystitis mice." (PMID 38415918, 2024). "Furthermore, when bacterial persistence does occur in the bladders of C3H/HeJ mice, it may be mechanistically distinct from chronic cystitis in TLR4 signaling-competent C3H mice." (PMID 20811584, 2010). "In our previous research, we have proved that the TLR4/p65/NLRP3 signal pathway was been excessively activated, and played a key role in the spinal neuroinflammation in CYP-induced cystitis rats." (PMID 38020203, 2023). "Further studies should explore specific mechanisms by which the LCN2, TLR-4, and JAK/STAT pathways participate in UPEC-induced inflammation to facilitate the development of effective therapies for cystitis." (PMID 36555403, 2022). "Nevertheless, further studies are imperative to explore the specific mechanism by which the LCN2, TLR-4, and JAK/STAT pathways participate in UPEC-induced inflammation, with the goal of developing more effective therapies for cystitis." (PMID 36555403, 2022). "In order to discover novel polymorphisms associated with UTIs, we PCR-amplified and sequenced the coding regions of 7 TLR pathway genes (TLR2, TLR4, TLR5, MYD88, TIRAP, TRIF, and TRAM) in subjects with a high frequency of cystitis or pyelonephritis episodes." (PMID 19543401, 2009). "This study demonstrated that miR‐9‐enreched MSCs derived exosomes alleviate neuroinflammaiton and cystitis‐induced bladder pain by inhibiting TLR4/NF‐κb/NLRP3 signal pathway in interstitial cystitis mice, which is a promising strategy against cystitis‐induced bladder pain." (PMID 38415918, 2024). "In addition, in bladder infection, UPEC induced activation of Toll-like receptor 4 (TLR4), which is known to lead to the production of proinflammatory cytokines, including IL-6 and IL-1β." (PMID 38301068, 2024). "Interestingly, we have recently demonstrated that in chronic pain patients, peripheral blood mononuclear cells (PBMCs) also have increased TLR2 and TLR4 responsiveness compared with pain-free participants, suggesting that this could be a potential pain biomarker." (PMID 24204973, 2013). "Chronic pain patients have increased peripheral blood mononuclear cell Interkeukin-1β production following TLR2 and TLR4 simulation." (PMID 24204973, 2013).
diabetic cardiomyopathy (19 papers, 2014 to 2025). Diabetic cardiomyopathy is a disorder of the heart muscle in people with diabetes. "Furthermore, MD1, a negative regulator of TLR4, when deleted, enhances AF susceptibility and induces atrial remodeling in diabetic cardiomyopathy mice through activation of the TLR4/NF-κB signaling pathway." (PMID 41357167, 2025). "Synergistic cardioprotective effects of TIL and syringin in diabetic cardiomyopathy through the interaction between the TLR4/NF-κB/NLRP3 and PGC1α/SIRT3 pathways have also been documented." (PMID 39388398, 2024). "The TLR4 signaling pathway plays an essential role in the pathogenesis of Diabetic Cardiomyopathy (DCM)." (PMID 36434877, 2022). "The most formal of an HMGB1/TLR4/IL-33 axis was recently shown in diabetic cardiomyopathy in mice where high glucose mediated cardiomyocyte HMGB1 release interacts with TLR4 on cardiac fibroblasts and results in decrease in IL-33." (PMID 28898270, 2017). "Compared with diabetic cardiomyopathy mice unfed with gut content, the expression of occludin, the cardiac function, and the number of goblet cells in diabetic cardiomyopathy mice fed by gut contents were higher, whereas TLR4/MyD88 pathway-related proteins and cardiomyocyte hypertrophy were reduced." (PMID 40362425, 2025). "In addition, syringin has been reported to exert cardioprotective effects in diabetic cardiomyopathy through the interaction of TLR4/NF-κB/NLRP3 and PGC1a/SIRT3 pathways." (PMID 35806462, 2022). "Here, we report inflammation-induced cell death mediated by inflammatory cells (macrophage and dendritic cells) and inflammasome formation (TLR4, NLRP3) and NLRP3 activators (Nek7 and GBP5) that cause cardiac cell death is the key player in the development and progression of diabetic cardiomyopathy." (PMID 34685620, 2021). "A cardiomyocyte HMGB1/fibroblast TLR4/IL-33 axis contributes to diabetic cardiomyopathy in mice." (PMID 28898270, 2017). "•Toll-like Receptor 4 may become a new target for the treatment of diabetic cardiomyopathy." (PMID 36434877, 2022). "Therefore, in this study, the authors used meta-analysis to observe the extent of myocardial injury in diabetic rats after the inhibition of TLR4 expression levels to provide evidence-based medical information for the treatment and prevention of diabetic cardiomyopathy." (PMID 36434877, 2022). "Image quantification showed a significant increase of TLR4 (p < 0.001) and NLRP3 (p < 0.001) expression levels in cardiac myocytes in the STZ-induced diabetic cardiomyopathy group compared to the control." (PMID 34685620, 2021). "BMP-7 treatment against inflammasome formation showed a significant reduction (p < 0.001) in the expression of TLR4 and NLRP3 as compared to the diabetic cardiomyopathy group." (PMID 34685620, 2021). "However, treatment with BMP-7 attenuates the expression of TLR4 (p = 0.027) and NLRP3 (p = 0.033) compared to the STZ-induced diabetic cardiomyopathy." (PMID 34685620, 2021). "In addition, a glucocorticoid (methylprednisolone) treatment reduced expression of TLR4/NF-κB signaling and IL-1β, IL-6, TNF-α, and ICAM-1 on T1DM-induced diabetic cardiomyopathy with I/R injury." (PMID 28659798, 2017). "Therefore, the relationship between TLR4 signaling and GLUT regulation in the heart is intriguing and further investigation may not only uncover new mechanisms for cardiac IR but also allow identification of novel therapeutic targets for diabetic cardiomyopathy." (PMID 25101057, 2014).